TLR4 (toll like receptor 4)
Diseases named in the same sentence as TLR4 in open-access papers (continued):
Sharing a sentence is not in itself a finding about the gene and the disease.
infection (continued). "Flow cytometry-based analysis showed that the surface expression of TLR4 was reduced upon infection and TAK-242 (1μM) treatment, significantly [from 75.87 ± 1.247 to 51.07 ± 0.6360% (CHIKV) and 53.5 ± 0.611% (TAK-242)]." (PMID 37153546, 2023). "This infection is TLR4- and CX3CR1-dependent and polarizes the differentiation of neonatal macrophages toward an M2-like phenotype." (PMID 37896776, 2023). "Lipopolysaccharide (LPS) sensing by Toll-like receptor 4 (TLR4) controls early responses to infection." (PMID 37817942, 2023). "S. Typhimurium resides within macrophage vacuoles and activates Tlr4 and the inflammasome during infection." (PMID 35638781, 2022). "In mammals, with the cooperation of the accessory receptor MD2, human TLR4 mediates the LPS signaling pathway participating in antibacterial infection." (PMID 36643915, 2022). "KEGG enrichment analysis showed that these downregulated proteins were primarily associated with the porphyrin metabolism involved in oteoarthrosis and the NF-κB and TLR4 pathways involved in infection." (PMID 36091838, 2022). "In EBOV studies, primarily human cells including HEK-293 and THP-1 cells were used, but a few studies using C57BL/6 mice for infection models still demonstrated a role for TLR4." (PMID 36680092, 2022). "This corroborates previous studies which showed that ROS production was essential in the TLR4-dependent innate clearance of B. pertussis in a murine infection model." (PMID 35646735, 2022). "Natural variation in other genes has also been shown to play a role in differential survival after STm infection, including neutrophil cytosolic factor 2 (Ncf2) and toll-like receptor 4 (Tlr4)." (PMID 35417454, 2022). "We used 30 multiplicity-of-infection TLR4 overexpression lentivirus in combination with puromycin to treat and screen chondrocytes." (PMID 35571243, 2022). "Our previous results revealed that TLR4‐MyD88 signalling controls IL10 production following Kp52145 infection." (PMID 36337046, 2022). "Several viruses, such as influenza A virus and human respiratory syncytial virus, have also been shown to activate p38 MAPK within 10 min of infection through recognition of pattern recognition receptors by toll-like receptor 4 and MyD88 during virus entry." (PMID 35463647, 2022). "For the first time, it was shown that TLR4 plays an important role during attachment step of TMUV infection." (PMID 36379254, 2022). "Third,as TLR4 plays a vital role in inflammation and infections, infection datainvolving other organs systems was missing in the current dataset." (PMID 39076193, 2022). "The results indicated that in the early stage of infection, the TLR4 signal controlled the expression of most genes in lung to cope with gram-negative bacterial infection." (PMID 36506034, 2022). "Infected blood-MØs evidence strong upregulation of membrane-associated TLR4 and cytoplasmatic NOD1 during the first 3 h of infection." (PMID 35053098, 2022). "A recent study demonstrated that the microbiota regulates microglia function through TLR4, priming these cells to respond to infection." (PMID 35326484, 2022). "The sex hormone, testosterone, can reduce TLR4 expression and sensitivity, which is proposed to explain in part the less optimal defence during infection in male compared to female." (PMID 35956081, 2022). "A recent study demonstrated a strong association between lectin-like oxidized-LDL receptor (LOX-1), TLR4, and the upregulation of reactive oxygen species (ROS), a direct attempt of the immune system to kill the fungus in response to infection." (PMID 36499260, 2022). "On the other hand, TLR4 inhibition promoted a significant reduction of IL-1β after infection with L. corymbifera and M. circinelloides and TNF-α in response to M. circinelloides." (PMID 36311802, 2022). "Upon infection, stimulation by LPS leads to TLR4 activation of the macrophages that leads to a series of immune responses." (PMID 35432369, 2022).
infection (continued). "Recent studies also illustrated that administration of LPS (a TLR4 agonist) at the time of infection offers partial protection against Bordetella pertussis in mice." (PMID 35986268, 2022). "While the survival rates of WT and Tlr2–/– mice were similar, all the Tlr4–/– mice died by 120 hours after infection." (PMID 36048544, 2022). "In this study, we employ this infection model together with other, less complex ex vivo/in vitro models to validate TLR4 modulators identified using a computational approach." (PMID 35208698, 2022). "The use of a TLR4 antagonist throughout all stages of infection promotes survival in mice infected with either mouse-adapted Ebola virus or Marburg virus." (PMID 36558734, 2022). "TLR4 has been reported to control the immune response to infection of epithelial cells that line the mucosa of the urinary tract and the signaling response of this TLR regulates cell balance and death by releasing some urothelium cytokines." (PMID 36506333, 2022). "TLR4 has been described as induced on the surface of host phagocytes after infection with virulent Mtb strains, such as H37Rv, and shedding in its soluble form by ADAM17 cleavage in pleural effusion from TB patients." (PMID 36679931, 2022). "Decreased expression of TLR-4 has been previously reported in elderly patients who have a higher prevalence of infection than younger patients." (PMID 35782930, 2022). "Kidney UPEC burden in TLR4‐sufficient C3H/HeN mice fed NH4Cl‐2%, was two to three orders of magnitude higher 3 days post infection (3 dpi) compared to mice fed normal chow." (PMID 36151614, 2022). "TLR4 constitutes one of the key players of the innate immune system, and is activated in response to an infection, resulting in NF-kB mediated production of pro-inflammatory cytokines, such as TNFα and IL-6." (PMID 36613673, 2022). "In the present study, E. coli inoculation led to enhanced mRNA levels of TLR4, -5 and -15 in spleen, indicating activation of the innate immune system in the spleen following the infection." (PMID 36198724, 2022). "These sGP molecules diffuse through the blood stream and can activate TLR4 on cells remote from the infection site." (PMID 36288690, 2022). "The vaccine design had a high affinity for the innate immune receptor (TLR-4), which aids in stimulating innate and adaptive immunity against pathogen infection." (PMID 35632446, 2022). "The protective capacity of TLR priming also differs by infection, as TLR4 priming with E. coli-derived LPS improves protection against lung infection with Klebsiella pneumoniae and influenza A virus, in contrast to S. pneumoniae." (PMID 35680890, 2022). "In hepatitis C virus (HCV) infection, the immune system enhances transcription, improves the expression of TLR4, activates B-cells, increases the secretion of IFN-β and IL-6, and induces inflammatory responses and antiviral effects." (PMID 36500406, 2022). "In fact, comparing the susceptibility of TLR2‐/‐, TLR4‐/‐, TLR9‐/‐ and C57BL/6 WT to L. major infection, TLR9‐/‐ mice are most susceptible to this infection." (PMID 35119120, 2022). "In the murine UTI model, TLR4 controls the innate immune response to Escherichia coli and TLR4 mice −/− develop asymptomatic bacteriuria instead of severe infection." (PMID 36506333, 2022). "In response to infection, the decidual blood vessels have been demonstrated to serve as first responders via Toll-like receptor-4 (TLR4) sensing." (PMID 36313741, 2022). "We first addressed the contribution of TLR2/TLR4 to the production of these antimicrobial compounds upon infection with leptospires." (PMID 35899053, 2022). "In this respect, several studies lined out the importance of TLR4 for Ct recognition by the host cell or clearance of Ct infection." (PMID 36557742, 2022). "The pretreatment of SRIP or duck primary cells with an anti-TLR4 antibody for 1 h at 4 °C significantly inhibited SRIP infection; up to 95% reduction of infection was observed for both treatments." (PMID 36379254, 2022).
infection (continued). "It has recently been shown that maternal TLR4 signaling is critical for infection-induced preterm birth." (PMID 36552269, 2022). "After infection with Aeromonas hydrophila, we found that the IL-10 and IL-11 expression levels were upregulated in each group, while TLR-4, MYD88, and TNF-α were down regulated." (PMID 36139830, 2022). "Others have shown that TLR4 can trigger an innate immune response that appears to be mediated by activated T-cells, infection, and pyroptosis (i.e., death by infection)." (PMID 36613731, 2022). "This is consistent with the phosphorylation of TBK1 and IRF3 within 30–60 min post infection following the activation of TLR4-TRAM-TRIF signaling." (PMID 35947948, 2022). "Comparing B6 and TLR4KO, GLY treatment reduced clinical scores and improved disease outcome after infection and decreased mRNA expression levels in cornea for TLR4, HMGB1, and RAGE in B6 mice." (PMID 36422579, 2022). "To that end, we used neutralizing antibodies to block TLR4 in C57BL/6 macrophages prior to infection." (PMID 35154115, 2022). "We also detected PKR phosphorylation upon infection in a TLR4-dependent and NE-dependent manner, undoubtfully linking TLR4 to PKR activation in the context of macrophage infection by L. donovani." (PMID 35154115, 2022). "LPS is known as a mediator participating in the process of immune responses and infection via Toll-like receptor 4-related signaling pathways." (PMID 35453467, 2022). "In a molecular docking experiment between an epitope vaccine and the viral protein-binding TLR4, the lowest energy score of 986.5 indicates the vaccine would have an infection-inhibitory function and would be tightly bound to the TLR4 receptor." (PMID 36298534, 2022). "At the beginning of the infection (1 h), despite the increase in TLR4 expression, there was a decrease in the expression of CD14 and LY96 (also known as MD-2), which are important for lipopolysaccharide recognition." (PMID 36296238, 2022). "This is consistent with our observations that NE and TLR4 co-localize with L. donovani at the point of entry in macrophages and remain co-localized in mature parasitophorous vacuoles 72 h after infection." (PMID 35154115, 2022). "This event is explained by the changes in signal transduction from binding to Toll-like receptor 4, changes in leukocyte subtypes, or maturation of cells during the infection process." (PMID 36969980, 2022). "The expressions of il10, nos2 and the ISGs isg15, and mx1 were only upregulated in tlr2−/− macrophages following infection, indicating that TLR4 controls the levels of these M(Kp) markers." (PMID 36337046, 2022). "This response during systemic or local infection is mediated mainly by interleukin 1 beta (IL-1β), a known pyrogen released in response to activation of TLR4 and the Nlrp3 inflammasome." (PMID 34853440, 2022). "Promising new approaches to combat infections and inflammatory diseases involve modulation of the host immune system via TLR4." (PMID 35208698, 2022). "In the urinary tract, TLR4 plays a central role in the innate host immune defense against E. coli, and its regulation is crucial to the clinical outcome of infection." (PMID 35857780, 2022). "Hypoxia, infection, and prematurity accentuate TLR4 expression in the intestinal mucosa creating an imbalance between pro-inflammatory and anti-inflammatory signaling." (PMID 35927380, 2022). "These bacteria likely modulate the expression of surface molecules (proteins, LPS) to avoid recognition through protective TLR2 and TLR4 and establish infection in the host." (PMID 34975922, 2021). "A study investigating the involvement of TLR2, TLR4, and MyD88 in pulmonary C. burnetii infection found a different role for these factors according to the site of infection." (PMID 34796128, 2021). "The relative protein level of TLR4 increased dramatically (p < 0.01) in the mice of the Inf.Unt group compared with the other groups at day 1, 5, and 15 post-infection." (PMID 35095858, 2021).
infection (continued). "Neu1-overexpression and siglec-E-silencing together followed by infection activated both MyD88 and TRIF-signaling through their enhanced TLR4-association." (PMID 33763070, 2021). "Similar to how the body responds to a pathogen-initiated infection, LPS is recognized by the toll-like receptor TLR4 to activate monocytes and macrophages, among other innate immune cells." (PMID 33731173, 2021). "TLRs are responsible for the recognition of pathogen-associated molecular patterns (PAMPs) during pathogen infection, such as TLR2 recognizing lipoproteins and glycolipids and TLR4 recognizing LPS." (PMID 33923441, 2021). "Most studies have shown that LPS or infection can induce autophagy via TLR4 signaling, and that the knock-down/knock-out of TLR4 down-regulates autophagy." (PMID 34746034, 2021). "In the present study, we showed that TLR4 plays an important role in the elimination of C. perfringens, indicating that TLR4 signaling is activated during infection." (PMID 33763386, 2021). "For example, the discovery of Toll-like receptor 4 (TLR4) in humans (1997) has revolutionized the field of infection biology and innate immunity." (PMID 33510592, 2021). "Accordingly, we overexpressed Neu1, which would desialylate and activate TLR4 and silenced siglec-E to prevent any binding with sialic acids which were followed by infection and confirmed by western blot analysis." (PMID 33763070, 2021). "As a key member of TLR family and a classic inflammatory mediator, TLR4 acts as a bridge molecule between innate and adaptive immunity, as well as between infection and inflammation." (PMID 34479599, 2021). "The bacteria-induced activation of TLR4 often leads to the production of multiple cytokines to protect against infection." (PMID 33966642, 2021). "Here, we demonstrate that disease in C3H mice during VEEV TC-83 infection is dependent on TLR4 because intranasal infection of C3H/HeN (TLR4WT) mice with VEEV TC-83 resulted in mortality as opposed to survival of TLR4-defective C3H/HeJ (TLR4mut) mice." (PMID 33487119, 2021). "In line with this, others reported TLR4−/− mice were protected from lethal infection by H1N1 influenza." (PMID 33498715, 2021). "In the clinical scenario, neonates are vulnerable to infection due to weakened immunity and rely on their innate immune system to combat any externally acquired infection and TLR4 is a crucial component of the neonatal immune system." (PMID 34445253, 2021). "Myeloid Differentiation factor 2 (MD2), a co-receptor of TLR4, governs the activation of TLR4 during the infection." (PMID 33869283, 2021). "In purified B cells, the expression of TLR4 and 7 increased significantly after infection (p < 0.05), especially the expression of TLR7 which increased nearly 3 times after infection." (PMID 34788282, 2021). "Trypanosoma cruzi experimental infection in TLR-deficient mice showed that TLR2, TLR4, TLR7, and TLR9 play a role in host resistance." (PMID 34336720, 2021). "During infection, TLR4 responds to the LPS present in tissues and the bloodstream and triggers pro-inflammatory reactions facilitating eradication of the invading bacteria." (PMID 33057840, 2021). "Compatible with the data obtained from analyzing the TRIF KD and KO, both TLR3 and TLR4 proved to be required for optimal production of IL-6 following infection with L. pneumophila." (PMID 34280250, 2021). "mRNA expression of both TLRs in the S. Gallinarum group was downregulated at 6 h post-infection, but this showed a peak at 24 h post-infection with fold-change being greater for TLR4 (6.82-fold) than for TLR21 (2.5-fold)." (PMID 34446765, 2021). "Second, we observed that infection with a L. pneumophila mutant bearing altered lipid A triggers a decreased, TLR4-dependent cytokine response, as did the LPS from that mutant." (PMID 34280250, 2021).
infection (continued). "In vitro studies revealed that cells lacking TLR4 are more susceptible to Kaposi sarcoma herpesvirus (KSHV) infection, whereas activation of TLR4 protects cells from infection." (PMID 33498715, 2021). "Bacterial endotoxins, as major components of Gram-negative bacterial outer membrane leaflets and a well-characterized TLR4-MD-2 ligand, are lipopolysaccharides (LPSs) that are constantly shed from bacteria during growth and infection." (PMID 34356705, 2021). "Ad-TLR4 infection more than compensated the reduction of TLR4 expression in the LKO cells and brought the levels of SREBP1a expression to those observed in WT cells." (PMID 33816466, 2021). "The results showed that the gene expression levels of TLR4 and NF-κB were significantly upregulated after the infection with A. hydrophila, indicating that TLR4 and NF-κB were activated." (PMID 34220849, 2021). "The stimulation of TLR4 was monitored upon infection with cells from the 042 wt, 042 aggR + FRT3′UTR and 042 aggR + FRT3′UTR ast fad strains." (PMID 34785760, 2021). "The overexpression of TLR4 strongly enhanced the percentage of endocytosis and capacity of elimination in monocytes during the early stages of infection." (PMID 33966642, 2021). "During infection TLR4 has been reported to be hypersialylated which probably serve as the ligands for siglec-E and subsequently initiates inhibitory signaling." (PMID 33763070, 2021). "We observed colocalization of MPyV (detected by VP1 capsid protein staining) and TLR4 as early as 2 h post-infection (2 hpi) at a high virus input (MOI = 10)." (PMID 33923020, 2021). "The frequency of L. braziliensis-infected cells and numbers of intracellular parasites were quantified in TLR2- and/or TLR4-neutralized monocytes from CL patients and HS at 2 and 48 hours post-infection." (PMID 34691019, 2021). "Because of the dependence of MMP-9 induction and BBB permeability during neurologic diseases on TLR4, the role of TLR4 during VEEV TC-83 infection was examined." (PMID 33487119, 2021). "Overexpression of Neu1 followed by infection was able to prevent sialic acid siglec-E interaction through TLR4 desialylation." (PMID 33763070, 2021). "YopJ is the major Yop effector responsible for the induction of pyroptosis in macrophages during infection and limits toll-like receptor 4 (TLR4) dependent signaling pathways." (PMID 34871329, 2021). "The results of the present study demonstrated that ISG15 inhibited the TLR4/NF-κB signaling pathway, and such temporary immune tolerance may lead to weakened identification of pathogenic microorganisms in the body during this period, thus increasing the risk of infection." (PMID 34573559, 2021). "TLR4 blockage on hMDMs resulted in an increase in the production of TNF-α upon infection of hMDMs with Sporothrix species." (PMID 34867977, 2021). "We further examined the TLR4-TRIF association in Neu1-overexpressed and siglec-E silenced co-transfected cells followed by infection as measured by co-immunoprecipitation." (PMID 33763070, 2021). "Conversely, interaction of MMTV with DCs via TLR4 would favor the infection by increasing the expression of the viral cell entry receptor CD7171." (PMID 34711839, 2021). "In our experiments, TLR4 was significantly upregulated in mRNA and protein levels by the infection and cleaved to sTLR4." (PMID 34439812, 2021). "The amniotic fluid infection with E. coli O55 upregulated the expression of TLR4 on the amniotic membrane compared to the expression in the non-infected amniotic membrane." (PMID 34439812, 2021). "Myeloid lineage cells, such as macrophages are known to express high levels of TLR4 as these innate immune cells can quickly respond to infection through the production of large amounts of chemotactic and inflammatory mediators." (PMID 33446670, 2021). "In previous studies, researchers mainly investigated the functions of TLR4 with regard to the activation of innate immune responses and production of proinflammatory cytokines during infection." (PMID 34746034, 2021).